NOTCH1 (notch receptor 1)
Diseases named in the same sentence as NOTCH1 in open-access papers (continued):
Sharing a sentence is not in itself a finding about the gene and the disease.
infection (continued). "In order to evaluate whether the decreased expression of erbB2 was controlled by M2 receptors directly or via the Notch-1 pathway, infection with recombinant adenovirus expressing the construct GFP-NICD was performed." (PMID 35204740, 2022). "Furthermore, the reduced progression abilities by Notch1 knockdown or DAPT treatment were restored after infection with miR-151-expressing adenoviruses in NUGC-3 cells, the cell with detectable cleaved Notch1 receptor." (PMID 27191259, 2016). "Interestingly, inhibition of NOTCH1 signaling resulted in elevated expression of infection-induced PD-L1 whereas inhibition of SHH signaling showed increased transcripts of JAG2 and NICD, markers for NOTCH activation." (PMID 27080341, 2016). "Following infection with an adenovirus over-expressing Notch1 intracellular domain (NICD), total BMSCs and c-KitPOS/NKX2.5POS cells were assessed for differentiation to cardiomyocyte, SMC, and endothelial cell lineages by immunofluorescence staining and real-time quantitative RT-PCR." (PMID 25956503, 2015). "Thus, the recombinant lentiviral vector of Notch1-shRNA-3 was selected for packaging and infection." (PMID 33971906, 2021). "Upon infection of ST cells and organoids (MOI of 1), the expression of NOTCH1 and JAG2 significantly decreased, in contrast to that of DLL4, whose expression increased." (PMID 41272765, 2025). "The use of 25 to 100 mg/kg of baicalin upregulated Notch 1, RBP-J, JAG1, and HES1 mRNA expression levels from the blood vessels compared to the infection group (p < 0.01)." (PMID 40427615, 2025). "Treatment with 2-pyridone PIM1 inhibitor was able to significantly downregulate Notch1, Notch2, CTNNB1, and CDC42 in SARS-CoV-2-infected cells at 24 h post-infection (p-value < 0.001)." (PMID 37211584, 2023). "SARS-CoV-2 infection resulted in a significant overexpression of Notch1, Notch2, CTNNB1, CDC42, and PSEN1 after 24 h of infection." (PMID 37211584, 2023). "Then, to assess the role of Notch-1 signaling in regulating apoptosis in MAP-infected macrophages, Caspase-3 activity was measured in DAPT pre-treated THP-1-derived macrophages prior infection with MAP." (PMID 32635645, 2020). "Further, early activation of NOTCH1 signaling on mycobacterial infection is in line with the current observation of NOTCH1 signaling inducing MSI at early time points of infection." (PMID 27532872, 2016). "Notch-1 signaling was shown to modulate macrophage polarization and immune defenses during infection, but the molecular mechanisms were not defined." (PMID 35357214, 2022). "Transfection of these cells with a Smad3 expression vector caused induction of p21WAF1/CIP1 expression while, conversely, knock-down of Smad3 by infection with shRNA retroviruses (pRS-Smad3 n°1 and n°2) showed that induction of p21WAF1/CIP1 by activated Notch1 is Smad3-dependent." (PMID 27384993, 2016). "Infection of HMLE-Raslow cells with retroviruses expressing AcN1 enabled selection for high level expression of AcN1, indicating that in the background of oncogenic Ras signaling, constitutively active Notch1 proteins are better tolerated in HMLE cells." (PMID 20030805, 2009). "Moreover, the two over-represented pathways nucleotine-like (purinergic) receptors and signaling by NOTCH1, at 6 h of infection, are not significantly over-represented at 16 h." (PMID 28993767, 2017). "In summary, establishing novel roles for SHH and NOTCH1 signaling pathways, we found mycobacteria-activated SHH signaling induces PD-L1 and COX-2-PGE2 to mediate the expansion of CD4+CD25+FoxP3+ Tregs whereas infection-induced NOTCH1 signaling was found to suppress the Treg expansion." (PMID 27080341, 2016).
infection (continued). "Here, mice carrying a T cell specific deletion of Notch1 (N1ΔCD4Cre), Notch2 (N2ΔCD4Cre) or both Notch1 and Notch2 (N1N2ΔCD4Cre) on a resistant C57BL/6 genetic background were infected with L. major to study the importance of Notch receptors in Th1 differentiation and resolution of the infection." (PMID 22396647, 2012). "The mRNA expression of Notch1, DLL1 and Hes1 were significantly higher in patients with moderate/severe TB compared to those with mild TB or no infection." (PMID 37063841, 2023). "Expression of Notch1 on IFNγ+CD4+T cells revealed an increase between days 7 and 14 of infection in lungs but not LNs." (PMID 35603470, 2022). "In absence of infection, treatment with DAPT (0–40 μM) resulted in a significant decrease in Notch-1 expression at 20–40 μM concentration levels compared to untreated macrophages (average 36%) (p < 0.05)." (PMID 32635645, 2020).
adenocarcinoma (20 papers, 2013 to 2025). A common cancer characterized by the presence of malignant glandular cells. "Finally, the presence of NOTCH1 private mutation in the adenocarcinoma component only in the primary site, in addition to a common mutation in PTEN gene shared by the adenocarcinoma component in primary and nodal metastasis, should support their/its role in inducing metastasis." (PMID 34926584, 2021). "The other genes that were much more mutated in SCC (with estimated mutation proportion in SCC and in adenocarcinoma, respectively) were LRP1B (23%, 10%), KMT2D (16%, 7%), FAT1 (15%, 5%), CDKN2A (12%, 2%), NOTCH1 (10%, 3%), and NFE2L2 (10% and 1%)." (PMID 34645806, 2021). "Notch1 also represents an independent prognostic factor in surgically resected adenocarcinoma patients with a major impact in combination with VEGF-A (Vascular Epidermal Growth Factor-Alpha) upregulation." (PMID 27847554, 2016). "Gain-of-function mutations in NOTCH1 or loss of the negative NOTCH regulator NUMB have been identified in up to 30% of adenocarcinomas and are correlated with poor prognosis." (PMID 30087852, 2018). "Thus, CK2 activity is sufficient and necessary for Notch reporter and gene target transactivation in adenocarcinoma cell lines, at least in part due to effects in Notch1 protein levels." (PMID 28134850, 2017). "Moreover, the concomitant expression of MYC led to a progression to adenocarcinoma and metastases, indicating a synergistic effect between Notch1 and other oncogenes." (PMID 27847554, 2016). "A meta-analysis confirmed positive correlations of NOTCH1 and 3 expressions with progression and worse OS in adenocarcinoma (but not in lung SQCC)." (PMID 30087852, 2018). "A different genetic profile emerged from the molecular analysis of the two additional adenocarcinoma nodules I3 and S1, lacking those somatic mutations identified in the mixed nodules, but shared two somatic missense mutations in the KRAS (p.Gly12Asp) and NOTCH1 (p.Pro498Arg)." (PMID 34926584, 2021).
hematological malignancies (19 papers, 2011 to 2025). "This is consistent with the observation that the cell cycle is dysregulated in NOTCH1-mutated hematological malignancies, which mainly arise from the upregulation of responsible cell cycle genes of the cyclin-dependent kinase families." (PMID 37833915, 2023). "Five of the nine NOTCH1 variants were known variants that had been found in hematologic malignancies (p.Arg1598Pro, p.Gln2503Ter, p.Glu2460Ter, p.Leu1585Gln, p.Phe1592Ser)." (PMID 33903686, 2021). "Targeted next-generation sequencing covering 172 genes reportedly mutated in hematological malignancies revealed NOTCH1 G881S and BCOR2 R1589H mutations: both germline." (PMID 33505919, 2020). "While in case of solid cancer, overexpression of Notch has been thought to be the causative factor; the gain-of-function mutations in Notch1 NRR have been shown to be the responsible factor in case of hematological malignancies." (PMID 26046801, 2015). "NOTCH1 mutations are prevalent in OSCCs, but in China, some of these variants are localized in the same domains where activating NOTCH1 mutations are described in hematologic malignancies, which suggest that NOTCH1 mutations can play opposite roles in different populations." (PMID 39613893, 2024). "Nevertheless, whether SAH-mAH2-5 can present identical or similar antitumor effects in vivo or whether it is also effective for hematological malignancies that are mostly caused by Notch1 gain-of-function mutations needs further validation." (PMID 37714834, 2023). "We found that the expression of Notch1 and Jagged1 is detected in various hematological malignancies by FCM." (PMID 23181106, 2012). "Because the coexistence of a driver clone and the acquisition of additional mutations have been identified repeatedly in hematologic malignancies, further studies are required to elucidate how SH2B3—GATA1 and NOTCH1—STAG2 mutations contribute to the pathogenesis of hypereosinophilia." (PMID 29088303, 2017). "Conversely, activation of NOTCH1 signaling through gain-of-function mutations in NOTCH1, first described in T-ALL, or loss-of-function mutations in NOTCH1 regulators, such as FBXW7 and NUMB, has been linked to therapeutic recalcitrance of hematologic malignancies." (PMID 22768113, 2012). "Compared with the patients with other hematological diseases, the patient had higher levels of LYL1, NOTCH1, PAX5, MYC, and E2B, all of which contribute to the development of T and B cells." (PMID 33126303, 2020). "In the current study, the cross talk among the Notch1 pathway, Ets-1, and TRPA1 in erythroid and megakaryocyte differentiation suggests a potential combinatorial strategy for treatment of hematological malignancies in the near future." (PMID 28220825, 2017). "ACACA, RARA, NOTCH1 and NUP214 are known to form translocations in various types of hematological malignancies while many other fusion genes involve suspected oncogenes, such as RPS6KB1 (RPS6KB1-TMEM49 and RPS6KB1-SNF8), GSDMB (TATDN1-GSDMB) and MCF2L (LAMP1-MCF2L)." (PMID 21247443, 2011).
kidney disease (10 papers, 2013 to 2024). "Thus, blockade of Notch1 signalling with DAPT or DBZ can be used as potential therapies for fibrotic kidney diseases." (PMID 31718671, 2019).
neurodegenerative disease (9 papers, 2016 to 2024). A disorder of the central nervous system characterized by gradual and progressive loss of neural tissue and neurologic function. "More specifically, 1, 1, 312, and 4 mutations in Notch1, Notch2, Notch3, and Notch4, respectively, were identified to be correlated with neurodegenerative diseases." (PMID 38790158, 2024). "To summarize, the present in silico study focused on analyzing mutations in Notch1–Notch4 proteins correlated with neurodegenerative diseases." (PMID 38790158, 2024). "Compromised Notch-1 expression is associated with some of the cardiovascular or neurodegenerative diseases." (PMID 35383529, 2022). "Additionally, through filtering the results of the HGMD database, all mutations in Notch1–Notch4 associated with neurodegenerative diseases were reported and imported." (PMID 38790158, 2024). "Additional studies are required to determine whether Notch1 signaling is involved in other melatonin-mediated protective effects in AD and other age-associated neurodegenerative diseases." (PMID 27630117, 2016). "Notch1 overexpression has previously been observed in other neurodegenerative diseases activation of the Notch signalling pathway has been found to play a role in ageing and memory." (PMID 31024234, 2019). "Abnormal Notch-1 signaling induces dysfunction of individual proteins and has an essential role in interactions of proteins in different neurodegenerative diseases." (PMID 27655677, 2016). "In recent studies, the Notch1 signaling pathway was identified as an important signaling pathway for normal adult brain function, as well as in AD and other neurodegenerative diseases." (PMID 27630117, 2016). "Recently, the Notch1 signaling pathway has been demonstrated to participate in aging processes and multiple age-related neurodegenerative diseases, such as AD." (PMID 27630117, 2016). "Nevertheless, it remains unknown whether Notch1 signaling is involved in the neuroprotective effects of melatonin in AD and other neurodegenerative diseases." (PMID 27630117, 2016). "A further comparative analysis of Notch1 expression/processing in different neurodegenerative diseases in humans is necessary to establish whether Notch1 may be considered a specific therapeutical biomarker for AD." (PMID 27364742, 2016). "Moreover, overexpression of Notch1 has been observed in several neurodegenerative diseases." (PMID 33799827, 2021). "EVs derived from human NP cells of patients with lumbar degenerative disease were found to promote MSC migration and differentiation into an NP-like phenotype via the Notch1 pathway, though the precise EV content responsible for this action is unknown." (PMID 37483952, 2023).
cardiovascular diseases (8 papers, 2008 to 2025). "NOTCH1 is implicated in cardiovascular diseases and is thought to have a dual role in carcinogenesis, depending on the specific cellular context." (PMID 40425987, 2025). "In recent years, the disrupted Notch-1 expression is associated with some neurodegenerative or cardiovascular diseases." (PMID 27655677, 2016). "Individuals with inactivating Notch1 mutations have a high rate of cardiovascular disorders, including valve stenosis and calcification." (PMID 19936191, 2008). "Laboratory evidence indicates that among the Notch receptors, Notch1/Hes1 signaling modulates not only cell proliferation but also apoptosis in the initiation and progression of tumors and cardiovascular diseases." (PMID 38703204, 2024). "In cardiovascular disease, celecoxib may be by Notch1/Hes1 signaling pathway to protect the heart from hypertrophy and inflammation." (PMID 40271123, 2025).
heart disease (8 papers, 2013 to 2025). "Inactivating NOTCH1 mutations are a rare cause of familial heart disease involving predominantly left ventricular outflow tract lesions and characterized by heterogeneity of clinical phenotype." (PMID 32720365, 2020). "Inactivating NOTCH1 mutations are a rare cause of familial heart disease involving predominantly left ventricular outflow tract lesions and characterized by the heterogeneity of clinical phenotype." (PMID 32720365, 2020). "Although the molecular mechanisms of action by Notch1 in aged C-MSCs remain to be characterized, our study emphasizes its importance not only in MI but also for aging heart diseases." (PMID 32154243, 2020). "A recent study reported that telomere shortening is a critical factor for age-dependent cardiac disease in the NOTCH1 haploinsufficiency mouse model." (PMID 29116081, 2017). "Although these probands were ascertained in the context of their CHD, our identification of NOTCH1 variants in family members without cardiac disease (e.g., in individuals with only cutis aplasia) indicates that the phenotypic spectrum of NOTCH1 variants extends beyond clinical CHD." (PMID 38778082, 2024).
lung (8 papers, 2010 to 2025). "We tested these conditional GEMM of lung ADC to determine if Sox9 expression is an early event downstream of Notch1 signaling." (PMID 25004243, 2014). "To validate the role of NOTCH1 in CRC, we administered DAPT to Ythdf1cki mice with AOM/DSS-induced colorectal tumorigenesis." (PMID 41423446, 2025).
Gastrointestinal Tumors (7 papers, 2016 to 2024). "Clinical trial 2: “A Biological Study of Resveratrol’s Effects on Notch-1 Signaling in Subjects with Low Grade Gastrointestinal Tumors” is the work of Emily R. Winslow from the University of Wisconsin, Madison." (PMID 28629161, 2017).
neurological disorders (6 papers, 2013 to 2025). "Dysregulation of NOTCH1 signaling has been implicated in several neurological disorders, including brain injury." (PMID 39129166, 2025). "The study concludes that targeting the Rbm24/Notch1 signaling axis could be a promising strategy for the treatment of early-stage PD and related neurological disorders." (PMID 39113792, 2024).
head and neck tumors (4 papers, 2013 to 2024). "Genomic studies of head and neck tumors have shown that although β-catenin is not frequently mutated in HNSCC, its activity is not inhibited by mutations in upstream gene encoding β-catenin, NOTCH1, FAT1, and AJUBA." (PMID 33469547, 2020).
hematopoietic cancers (4 papers, 2017 to 2023). "We found enrichment in NOTCH1 missense mutations in the PEST and the Lin-12/NOTCH repeat 3 (LNR3) domains relative to the expected numbers, which was consistent with reports that mutations in these regulatory regions lead to NOTCH1 activation in hematological cancers." (PMID 33322834, 2020).
metabolic disease (4 papers, 2016 to 2023). A congenital disorder (due to inherited enzyme abnormality) or acquired (due to failure of a metabolically important organ) disorder resulting from an abnormal metabolic process. "We observed that smoking-DMS in CYP1A1 and NOTCH1 were significantly associated with measures of metabolic disease risk." (PMID 30342560, 2018). "A similar expression pattern was detected in the white adipose tissue of obese and diabetic mice, suggesting a positive correlation between the expression of Notch1 and lipid accumulation and metabolic diseases." (PMID 26786165, 2016).
benign tumors (3 papers, 2017 to 2024). "The mean percentage of NOTCH1-positive expression in benign tumors was comparable to that in precancerous lesions (p = 0.562)." (PMID 39063983, 2024). "The elevated NOTCH1 expression in benign tumors suggests a potential role in the early stages of tumorigenesis." (PMID 39063983, 2024). "A comparison of the mean percentages of NOTCH1-positive expression between histological statuses revealed that the positive expression in precancerous and benign tumors was significantly higher than that in normal histology (p = 0.043 and p = 0.030, respectively)." (PMID 39063983, 2024). "NOTCH1 expression was only elevated in benign tumors compared to normal tissue." (PMID 39063983, 2024).
genetic disorder (3 papers, 2020 to 2024). "However, this challenge is not unique to NOTCH1-related disorder, as genotype-first approaches continue to redefine the phenotypic spectrum of many genetic disorders." (PMID 38778082, 2024).
proliferative retinopathy (3 papers, 2021 to 2025). "Having explored the relationship between Notch1 inhibition and CYP2J2, we next explored the mechanisms of a Notch1 agonist and CYP2J2 in hypoxia-induced retinopathy." (PMID 34666595, 2021).
vascular disorder (3 papers, 2011 to 2024). A general term used to describe any disease affecting blood vessels]. "A connection here (darkened) to this WVF/ADAMTS13 axis is reported for NOTCH1 which has roles in vascular epithelium, vascular disorders, and BBB function." (PMID 33946285, 2021). "DLL4/NOTCH1/PPARγ agonists and/or PI3K/AKT antagonists are attractive therapeutic targets for preventing or even possibly reversing progressive pathologic vasculopathy in PAH." (PMID 38903104, 2024). "As inhibition of Notch signaling with Notch1 decoy blocked the induction of MMP9 and MT1-MMP transcripts in HUVEC, blocking Notch signaling in pathological settings may perturb angiogenesis and may prove therapeutically useful in the treatment of vascular disorders." (PMID 21349159, 2011).
CNS tumors (2 papers, 2024). "The most commonly overexpressed genes in CNS tumors included TOP2A (67%), BIRC5 (59%), CDK4 (50%), BRIP1 (49%), NOTCH1 (41%), SMO (39%), and TP73 (39%)." (PMID 38347552, 2024).
inflammation (2 papers, 2015 to 2023). Aberrant reaction of the microcirculation characterized by movement of fluid and leukocytes from the blood into extravascular tissues. "Further research found that deletion of myeloid Notch1 activity triggers RhoA/ROCK signaling and aggravates liver inflammation." (PMID 37370115, 2023).